INS (insulin)
Diseases named in the same sentence as INS in open-access papers (continued):
Sharing a sentence is not in itself a finding about the gene and the disease.
glioblastoma (24 papers, 2013 to 2025). The most malignant astrocytic tumor (WHO grade IV). "Here, we describe in a Drosophila model how glioblastoma cells produce ImpL2, an antagonist of the insulin pathway, which targets neighboring neurons and causes mitochondrial disruption as well as synapse loss, both early symptoms of neurodegeneration." (PMID 33526430, 2021). "Insulin is a known regulator of SCD expression, and sensitivity to SCD inhibition in glioblastoma has been linked to increased ERK phosphorylation, also a downstream target of RTK signaling." (PMID 39187579, 2024). "Taken together, our findings using GNPs coated with insulin and a targeting antibody can have a large impact on facilitating delivery of targeting agents to glioblastoma, and lead to effective radiosensitization." (PMID 36324626, 2022). "Another differentially upregulated system in D10-017 compared to D317 is the insulin signaling pathway, which plays a role in glioblastoma survival and confers resistance to EGFR inhibitors." (PMID 35456993, 2022). "Here, we demonstrated that adding cetuximab and insulin-coated GNPs to standard of care therapy led to considerable damage to glioblastoma tumor tissue, and decreased its vascularization, proliferation, and repair." (PMID 36324626, 2022). "In one study, IGF-1 and insulin stimulated the growth of glioblastoma cells at 0.7 nmol/L and 80 pmol/L, respectively, which is well within the concentration ranges found in glioblastoma cyst fluid in the present study." (PMID 35659255, 2022). "Glioblastoma cells lines that rely on the insulin signaling pathway for their aggressive growth phenotype will be more affected by drugs that target the insulin signaling pathway." (PMID 25884993, 2015). "For the remaining initial conditions, the insulin signaling system in glioblastoma was robust over changes in initial HIF1α concentrations and the (IGFI-IGFBP2) complex concentration." (PMID 25884993, 2015). "Here, we developed a computational model of insulin signaling in glioblastoma in order to study this pathway’s role in tumor progression." (PMID 25884993, 2015). "We have developed a chemical-kinetic model that predicts glioblastoma growth as a function of insulin signaling." (PMID 25884993, 2015). "Using the model, we systematically test contributions of different insulin signaling protein interactions on glioblastoma growth." (PMID 25884993, 2015). "In sum, we have found a possible target in the insulin signaling system that merits exploration as a candidate drug target for glioblastoma patients and other patients with cancers sensitive to the insulin signaling pathway." (PMID 25884993, 2015). "Both the term vs preterm and the male vs female comparisons showed an enrichment in myometrial relaxation and contraction pathway, insulin signalling and signalling pathways in glioblastoma." (PMID 26419829, 2015). "In this study we connect for the first time microscale insulin signaling activity with macroscale glioblastoma growth through the use of computational modeling." (PMID 25884993, 2015). "One promising potential target is the insulin signaling pathway, which is known to contribute to glioblastoma progression." (PMID 25884993, 2015). "By using two different glioblastoma cell lines in our analysis, we have found that glioblastoma growth through the insulin signaling pathway is tumor specific." (PMID 25884993, 2015). "Insulin treatment of U87 glioblastoma cells, which had been serum-starved for 18 h, resulted in the significant stabilization of DUSP10 as compared to control, unstimulated cells." (PMID 25568665, 2014). "This supports previous findings showing that activation of insulin-mediated signalling pathways in glioblastoma promotes proliferation and survival of the tumour cells through PI3K/Akt and anti-glycemic therapy has been recently shown to enhance PI3K inhibitor efficacy in glioblastoma patients." (PMID 39915814, 2025).
glioblastoma (continued). "Furthermore, activation of the PI3K/Akt pathway by insulin has been shown to stabilize DUSP10/MKP5 in glioblastoma." (PMID 40002789, 2025). "This is likely due to the effects of glucose levels on glioblastoma cells and tumor growth, or due to the hyperinsulinemia that often accompanies hyperglycemia (insulin, a member of a family of growth factors, may itself promote tumor growth)." (PMID 37444478, 2023). "Thus, we created for the first time, a computational chemical-kinetic model linking the insulin signaling pathway to glioblastoma growth." (PMID 25884993, 2015). "However, drugs targeting this pathway have shown mixed results in clinical trials, and the detailed mechanisms of how the insulin signaling pathway promotes glioblastoma growth remain to be elucidated." (PMID 25884993, 2015). "However, while the process of invasive glioblastoma progression has been extensively studied macroscopically, it has not yet been well characterized with regards to intracellular insulin signaling." (PMID 25884993, 2015). "The computational model revealed how inhibition of specific molecular interactions in the insulin signaling pathway could lead to significant reduction of glioblastoma growth." (PMID 25884993, 2015). "Additionally, it has been established that abnormal insulin signaling accelerates glioblastoma growth, and inhibiting this pathway may provide an alternative therapy to the existing standard care." (PMID 36295107, 2022). "Furthermore, glioblastoma progression requires insulin pathway attenuation in neurons." (PMID 33526430, 2021). "HECTD1 is a HECT domain E3 ubiquitin ligase and is widely expressed in a range of human and murine primary cells and cell lines, including GBM (glioblastoma multiforme) cell line LN-229, macrophages, and insulin secreting β-cells." (PMID 33781347, 2021). "Thus, targeting the insulin signaling pathway through the IGFBP2-HIF1α interaction could be effective for those glioblastoma cells dependent on insulin signaling." (PMID 25884993, 2015). "Here, we show for the first time that our insulin-coated GNPs retain this BBB-crossing ability even after additional antibody conjugation, and effectively shuttle a glioblastoma-targeting antibody across the BBB." (PMID 36324626, 2022). "Intravenously injected GNPs coated with insulin and cetuximab (CTX-INS-GNPs) showed successful crossing of the BBB and high accumulation within an orthotopic glioblastoma in mice." (PMID 36324626, 2022). "Conversely, if the glioblastoma cells do not rely on the signaling from insulin for their growth, then targeting the insulin signaling pathway would not be effective in controlling the growth." (PMID 25884993, 2015). "According to the regulation of CLEC5A on Akt phosphorylation in glioblastoma cell lines, we further determined whether inhibition of Akt by Akt pathway inhibitors or activation of AKT by insulin signalling agonist could reverse the effects conducted by CLEC5A shRNA knockdown or overexpression." (PMID 30834619, 2019). "Besides its circulating insulin-lowering effects that reduce fasting blood glucose levels, basic investigations demonstrated that METF also inhibited the growth of various human cancer cell types, such as thyroid, prostate, gastric, breast and glioblastoma." (PMID 25375092, 2014).
ovarian dysfunction (24 papers, 2010 to 2026). The inability of the ovaries to function. "These ovarian dysfunctions were associated with increased fat deposition and impaired glucose-insulin axis." (PMID 33953699, 2021). "Comprehensively, excessive insulin overwhelms theca cell steroidogenesis, inducing abnormal production of ovarian androgens and causes subsequent ovarian dysfunction." (PMID 32585861, 2020). "New therapeutic options, like use of Inositols (i.e., insulin-sensitizing compounds) for assisted reproduction, might improve the chance of obtaining qualitatively good oocytes from CCSs at risk of ovarian dysfunction." (PMID 39133666, 2024). "Polycystic Ovarian Syndrome (PCOS) is a multifaceted metabolic and hormonal condition that impacts women in their procreative ages, identified by ovarian dysfunction, hyperandrogenaemia overweight and insulin insensitivity." (PMID 39294254, 2024). "It improved lipid metabolism, glucose tolerance, insulin resistance, hormonal imbalance, ovarian dysfunction, and adipocyte abnormalities." (PMID 39376609, 2024). "Many patients with PCOS exhibit decreased insulin sensitivity, which exacerbates metabolic abnormalities and may further enhance hyperandrogenemia and ovarian dysfunction." (PMID 39376609, 2024). "Furthermore, unbalanced levels of anti-inflammatory and proinflammatory cytokines contribute to ovarian dysfunction, reduce insulin sensitivity, and induce insulin accumulation." (PMID 36017323, 2022). "The expandable data obtained revealed that women that consume foods cooked at higher temperatures and with high AGE contents had significantly higher levels of total testosterone, insulin, androstenedione, and irregular menstrual cycles, relating them to ovarian dysfunction." (PMID 31861217, 2019).
polyneuropathy (24 papers, 2009 to 2025). A disease or disorder affecting more than one nerve. "Presence of diabetic macrovascular complications, polyneuropathy and insulin therapy were associated with higher Ang-2 levels (p < 0.05)." (PMID 21699724, 2011). "Targeting normal fasting levels of blood glucose with insulin in adults has previously shown to protect against critical illness-induced polyneuropathy/myopathy, an important cause of limb and respiratory muscle weakness, and a complication that prolongs the need for mechanical ventilation." (PMID 32867803, 2020). "In the univariate analysis, age, sex, MHR, neutrophil, HbA1c, disease duration, insulin use, and statin use were demonstrated to be possible confounding factors for the polyneuropathy." (PMID 30334993, 2018). "The GLP-1 RAs group predominantly has polyneuropathy and CKD, and received insulin in the greatest percentage." (PMID 41007868, 2025). "Relative to diabetic patients without polyneuropathy, DPN patients featured higher HbA1c values, as well as insulin and statin use rates (P = .001, P = .003, P = .028, respectively)." (PMID 30334993, 2018).
celiac disease (23 papers, 2008 to 2026). An autoimmune genetic disorder with an unknown pattern of inheritance that primarily affects the digestive tract. "Clinical characteristics, growth parameters, insulin doses, celiac autoantibody titers, and HbA1c levels throughout the first year after diagnosis of celiac disease were obtained from the medical records." (PMID 40655315, 2025). "Children and adolescents with T1DM and celiac disease had lower insulin requirements and growth parameters at the diagnosis of celiac disease." (PMID 40655315, 2025). "The purpose of this paper was to evaluate the prevalence of tTGA IgA positivity and possible celiac disease in T2DM patients with poor glycemic control (HbAlc value >7%) despite receiving insulin treatment." (PMID 28985731, 2017). "Lower insulin requirements at diagnosis of celiac disease might be attributed to malabsorption of nutrients, including glucose, secondary to intestinal mucosal damage." (PMID 40655315, 2025). "Similarly, Saadah found that children with T1DM had lower daily insulin doses at diagnosis of celiac disease, with a significant increase in their insulin requirements over the following 12 months." (PMID 40655315, 2025). "As people with Coeliac disease usually have a lower abundance of F. prausnitzii, an increase in its proportions could improve gut inflammation and metabolic markers like insulin sensitivity." (PMID 33923841, 2021). "Type 2 diabetic patients with inappropriate control of glycemia in spite of insulin treatment might be additionally tested for Celiac disease especially if they have low C-peptide levels." (PMID 28985731, 2017). "Additionally, insulin levels in milk appear to have a beneficial effect on gut maturation and prevent later diseases such as Crohn’s disease, celiac disease and type 1 diabetes." (PMID 28794439, 2017). "Type 2 diabetic patients with poor control of glycemia in spite of insulin treatment might be additionally tested for Celiac disease if they have low C-peptide levels." (PMID 28985731, 2017). "Improved glycemic control, reduced insulin response, increased satiety, enhanced nutritional quality, and support for gastrointestinal disorders like IBS and celiac sprue." (PMID 40755505, 2025). "Autoantibodies (anti-islet cell antibody, anti-insulin antibody, and anti-GAD antibody) were assessed in the patients diagnosed with celiac disease." (PMID 28985731, 2017). "However, several other studies reported no significant changes in insulin doses or HbA1c levels before and after diagnosis of celiac disease." (PMID 40655315, 2025). "Celiac disease patients with a concomitant DM1 may find it more difficult to cope with the demanding diet while already needing to concentrate to continuous daily glucose level monitoring, carbohydrate calculation and insulin dosing." (PMID 27457377, 2016). "Subjects were excluded due to: incomplete data, moving to another region, or diagnosis outside Auckland; insulin pump therapy within the first 2 years of the study period; coeliac disease; absence of T1DM antibodies; and syndromes affecting intellectual capacity." (PMID 21966469, 2011).
chronic hepatitis C (23 papers, 2009 to 2024). "Viral hepatitis often causes an increase in TNF-α, which can negatively affect insulin function through phosphorylation or increased levels of soluble TNF-α receptors that are often seen in patients with chronic hepatitis C." (PMID 36768699, 2023). "Reduced survival was mainly found in patients requiring insulin or having underlying chronic hepatitis C infection." (PMID 36164711, 2022). "We previously shown that adding metformin to peginterferon and ribavirin was safe and improved insulin sensitivity in chronic hepatitis C patients." (PMID 23133528, 2012). "In order to assess the direct role of HCV on the mechanisms of action of insulin in different areas (leukocytes and liver tissue), we studied a selected group of patients with chronic hepatitis C infection." (PMID 22830036, 2012). "Observational studies more than a decade ago demonstrated that a SVR achieved with interferon alpha plus ribavirin in patients with chronic hepatitis C could improve glycemic control and insulin sensitivity and possibly even prevent DM." (PMID 32395351, 2020). "TNF-α is upregulated in patients with chronic hepatitis C (CHC) and this cytokine has been shown to interrupt insulin signaling via reduced-tyrosine phosphorylation of IRS-1 and decreased ability of IRS-1 to associate with the insulin receptor." (PMID 23049551, 2012). "Inhibition of HCV improves peripheral insulin sensitivity in non-diabetic, lean individuals with chronic Hepatitis C without significant fibrosis." (PMID 39459866, 2024). "As might be expected based on all these data, antiviral treatment of patients with chronic hepatitis C improves insulin function in both diabetic and nondiabetic patients." (PMID 36768699, 2023).
glomerulosclerosis (23 papers, 2011 to 2025). A hardening of the kidney glomerulus caused by scarring of the blood vessels. "Among the PPAR isoforms, PPAR-γ activation has been shown to improve insulin sensitivity, reduce renal inflammation, and inhibit profibrotic signaling, thereby attenuating glomerulosclerosis and tubulointerstitial fibrosis in DKD." (PMID 40995593, 2025). "Recent reports of adult-onset ablation of GH action in fully grown mice have resulted in marked increase of lifespan, improved insulin sensitivity, decreased glomerulosclerosis, and cancer incidence in a sex-specific manner." (PMID 37442239, 2023). "In comparison to BTBR-WT mice, ob/ob mice demonstrated elevated bodyweight, increased blood glucose/insulin levels, urinary albumin and immunoglobulin G levels, glomerulosclerosis, reduced nephrin abundance and a damaged proximal tubule brush border." (PMID 29244860, 2017). "AS-IV also normalized glucose tolerance and insulin sensitivity, improved renal function, and ameliorated glomerulosclerosis and renal inflammation in db/db mice." (PMID 28066247, 2016). "As expected, tubulointerstitial fibrosis index (TFI) and glomerulosclerosis index (GI) scores were significantly higher in the kidney tissues from DM rats compared to CTRL or DM + INS (n = 6–10, p≤ 0.05)." (PMID 27101382, 2016). "Although PKCε deficient mice are viable, they display several phenotypes, such as impaired cutaneous wound closure, improved glucose-induced insulin secretion and reduction of insulin clearance, and glomerulosclerosis and tubulointerstitial fibrosis." (PMID 23639204, 2013). "Physical activity can improve insulin sensitivity, reduce nitric oxide (NO) degradation by increasing NO generation, and decrease ROS production, thus enhancing glomerular filtration function and ameliorating glomerulosclerosis and tubulointerstitial fibrosis." (PMID 39731593, 2024). "Similar to erlotinib-treated eNOS–/–db/db and waved 2 eNOS–/–db/db mice, waved 1 mice crossed to eNOS–/–db/db mice also had marked decreases in gain of body weight, fasting blood glucose, islet macrophage infiltration, and glomerulosclerosis and preserved pancreatic insulin levels." (PMID 36359813, 2022). "Similar to erlotinib inhibition of EGFR, homozygous waved 2 mice crossed to eNOS–/–db/db mice exhibited decreased gain of body weight, lower fasting blood glucose, preserved pancreatic islet insulin levels, less islet macrophage infiltration, and less glomerulosclerosis." (PMID 36359813, 2022). "Reduced insulin sensitivity is observed in glomeruli of obese and diabetic rats and normal insulin signaling seems critical for podocyte function and survival as podocyte-specific insulin receptor knockout mice develop albuminuria and glomerulosclerosis." (PMID 25386168, 2014). "Elevated insulin levels also stimulate the renin–angiotensin–aldosterone system (RAAS), contributing to increased glomerular pressure, endothelial injury, and glomerulosclerosis." (PMID 39940350, 2025). "It is worth mentioning that the combined administration of insulin and REO resorted to the normal glomerulosclerosis index of the kidney." (PMID 37016650, 2023). "Our findings are consistent with those from previous studies for GS‐444217, which showed that both drugs improved glomerular sclerosis, without affecting blood glucose levels and insulin sensitivity." (PMID 38873818, 2025). "For influence on the renal function, it is reported that mizoribine inhibited infiltration of macrophages into the glomerular and the interstitium and then inhibited glomerular sclerosis and interstitial fibrotic changes in a dose-dependent manner in insulin-nonresistant diabetic rats." (PMID 26433884, 2015).